NPC1L1 (NPC1 like intracellular cholesterol transporter 1)
Diseases named in the same sentence as NPC1L1 in open-access papers (continued):
Sharing a sentence is not in itself a finding about the gene and the disease.
epithelial ovarian cancer (3 papers, 2022 to 2025). "It is possible that circulating cholesterol is not the cause of the observed relationship between HMG-CoA reductase inhibition and ovarian cancer due to the lack of genetically close inhibition between NPC1L1 and PCSK9 inhibition and genetically close LDL cholesterol levels." (PMID 36034854, 2022).
hepatic disorder (3 papers, 2019 to 2025). "Therefore, to investigate whether hepatic NPC1L1 could increase the risk for hepatic disorders is an important issue." (PMID 32123832, 2019). "Our research highlights the potentially therapeutic effects of NPC1L1 inhibitors on portal hypertension, potentially through the inhibition of tissue factor." (PMID 40596422, 2025). "Nevertheless, due to the species differences in NPC1L1 tissue distribution, the pathophysiological impact of hepatic NPC1L1 on liver diseases has been overlooked in a lot of previous studies using murine models." (PMID 31883528, 2019).
lipid metabolism disorders (3 papers, 2025 to 2026). "The search for rare variants (gnomAD frequency less than 1 %) in the ABCA1, ABCG1, ABCG5, ABCG8 and NPC1L1 genes was performed using targeted sequencing data for 169 patients with lipid metabolism disorders." (PMID 42253452, 2026). "The aim of this work was to study the spectrum of rare variants in the cholesterol transporter genes ABCA1, ABCG1, ABCG5, ABCG8 and NPC1L1 that occur in patients with lipid metabolism disorders in the population of the Northwestern region of Russia." (PMID 42253452, 2026). "The small-molecule peptides in the earthworm protein hydrolysate alleviated lipid metabolism disorders in steatotic hepatocytes by regulating the expression levels of crucial proteins (APOC3, HMGCR, PCSK9, PPAR-Y, SREBP1, C/EBP-a, NPC1L1, CYP7A1)." (PMID 40647090, 2025).
prostate carcinoma (3 papers, 2022 to 2025). A carcinoma that arises from epithelial cells of the prostate gland. "We firstly applied drug target MR to investigate the association of genetically proxied lipid-lowering drug targets (HMGCR, PCSK9, and NPC1L1) with overall prostate cancer risk." (PMID 36595504, 2023). "Genetically proxied inhibition of NPC1L1 was associated with higher overall prostate cancer risk which likewise had a 95% CI that included the null (OR = 1.34, 95% CI = 0.87 to 2.04, P = 0.180)." (PMID 36595504, 2023). "A team has found that treatment of prostate cancer patients with NPC1L1 inhibitor Ezetimibe promoted the infiltration of CD8+ T cells into prostate tumors." (PMID 40430847, 2025). "Formal evaluations using coloc also found little evidence for colocalization between the expression of HMGCR or NPC1L1 in liver and prostate cancer at the respective genes (H4 = 0.33% for HMGCR, H4 = 0.38% for NPC1L1)." (PMID 36595504, 2023). "Additional LocusZoom plots visualising genetic variants associated with LDL-c and prostate cancer at PCSK9, HMGCR, and NPC1L1 genes provided similar results." (PMID 36595504, 2023). "In contrast, genetically proxied inhibition of PCSK9 (OR: 0.81; 95% CI 0.73–0.90; P < 0.001) but not HMG-CoA reductase and NPC1L1 was negatively associated with prostate cancer." (PMID 35151363, 2022). "The aim of this study was to examine the association between genetically proxied inhibition of lipid-lowering drug targets (i.e., PCSK9, NPC1L1, HMGCR) and prostate cancer using evidence from multiple datasets and analytical methods." (PMID 36595504, 2023). "In the main analysis of prostate cancer, fixed-effect IVW models were used for HMG-CoA reductase and NPC1L1 because of no heterogeneity, while random effect IVW model was also used for PCSK9." (PMID 35151363, 2022).
COVID-19 (2 papers, 2021). A disease caused by infection with severe acute respiratory syndrome coronavirus 2. "Therefore, we performed two-sample MR analysis in this study to test the association of lipid‐lowering drugs (HMGCR inhibitiors, PCSK9 inhibitiors, and NPC1L1 inhibitior) with COVID-19 outcomes (susceptibility, hospitalization and very severe disease)." (PMID 34866576, 2021). "The effect of NPC1L1 inhibitor on COVID-19 susceptibility may be worth further studies as well." (PMID 34866576, 2021). "We aimed to assess the causal effect of lipid-lowering drugs (HMGCR inhibitiors, PCSK9 inhibitiors, and NPC1L1 inhibitior) on COVID-19 outcomes using two-sample Mendelian randomization (MR) study." (PMID 34866576, 2021). "Strong evidence was observed between NPC1L1-mediated LDL cholesterol and the risk of COVID-19 susceptibility (OR = 2.02, 95% CI = 1.30–3.13; p = 0.002)." (PMID 34866576, 2021). "Firstly, there are no available eQTLs in blood for NPC1L1, so we were not able to explore the association between NPC1L1 expression in blood and COVID-19 outcomes." (PMID 34866576, 2021).
gastric cancer (2 papers, 2021 to 2025). A primary or metastatic malignant neoplasm involving the stomach. "For GC, our findings suggest that NPC1L1 expression or NPC1L1‐mediated LDL increases the risk of gastric cancer, providing strong evidence for the association." (PMID 40443776, 2025). "Additionally, a positive association was observed between NPC1L1 expression or LDL mediated by NPC1L1 and the risk of gastric cancer." (PMID 40443776, 2025).
hypertriglyceridemia (2 papers, 2014 to 2023). A laboratory test result indicating elevated triglyceride concentration in the blood. "As suggested by the effect of ezetimibe, an NPC1L1 inhibitor on postprandial hypertriglyceridemia, NPC1L1 inhibition may also lead to the reduction in intestinal triglyceride production Totum-070 reduced cholesterol uptake in vitro, and this effect was blunted by co-incubation with ezetimibe." (PMID 38140315, 2023).
liver cancer (2 papers, 2022 to 2025). An epithelial or non-epithelial malignant neoplasm that arises from the liver. "LDL mediated by NPC1L1 showed a positive correlation with EC (OR = 6.50, 95% CI: 1.34–31.42, p = 0.02), GC (OR = 20.17, 95% CI: 7.23–56.30, p < 0.01), CRC (OR = 2.64, 95% CI: 1.64–4.26, p < 0.01), and liver cancer (OR = 9.25, 95% CI: 2.11–40.51, p < 0.01)." (PMID 40443776, 2025).
Niemann-Pick disease, type C1 (2 papers, 2012 to 2016). Type C Niemann-Pick disease associated with a mutation in the gene NPC1, encoding Niemann-Pick C1 protein. "Three known genes, TLR4 interactor with leucine rich repeats (TRIL), Niemann-Pick disease, type C1, gene-like 1 (NPC1L1), and C4orf7 also termed follicular dendritic cell secreted protein were selected by three of the four methods." (PMID 22606341, 2012). "The genes contributing to these GO pathways in the DILGOM sample were ATP-binding cassette, sub-family G, member 1 (ABCG1), caveolin 1 (CAV1), Niemann-Pick disease, type C1 (NPC1), and Niemann-Pick disease, type C1, gene-like 1 (NPC1L1), while in the experimental SR study they were ABCA1 and NPC1." (PMID 27102866, 2016).
phytosterolemia (2 papers, 2021). "Here, we utilized NPC1L1 knockout (KO) mice to determine if reducing phytosterol absorption by genetic inactivation could relieve phytosterolemia associated pathologies, including mortality." (PMID 34465831, 2021). "Given that NPC1L1 genetic inactivation resulted in even lower phytosterol levels raises the possibility that a more potent inhibitor of NPC1L1 mediated phytosterol transport could lower phytosterol levels further and be a more efficacious therapy to treat phytosterolemia." (PMID 34465831, 2021). "Our work additionally reveals that a maximum efficacious dose of ezetimibe does not completely inhibit NPC1L1 mediated phytosterol transport in mice with phytosterolemia." (PMID 34465831, 2021).
sarcopenia (2 papers, 2024). Progressive decline in muscle mass due to aging which results in decreased functional capacity of muscles. "In this study, we conducted comprehensive drug target MR analysis to evaluate the causal effects of the most commonly prescribed lipid-lowering drug classes including HMGCR, PCSK9, and NPC1L1 inhibitors on sarcopenia risk." (PMID 38961447, 2024). "We did not observe an association between LDL and ALM and did not identify support for the repurposing of lipid‐lowering drugs that inhibit HMGCR and NPC1L1 to delay or prevent sarcopenia risk." (PMID 39254080, 2024). "This MR study did not support the repurposing of lipid‐lowering drugs that inhibit HMGCR and NPC1L1 to delay or prevent sarcopenia risk." (PMID 39254080, 2024). "While our findings offered valuable insights, large-scale and well-designed cohort studies in real-world settings are still imperative to examine the causal effects of long-term use of HMGCR, PCKS9, and NPC1L1 inhibitors on sarcopenia." (PMID 38961447, 2024). "Besides statins, the recent approval of PCSK9, and NPC1L1 inhibitors has led to a dearth of long-term adverse reaction data for risk of sarcopenia." (PMID 38961447, 2024). "There was little statistical evidence of an association between HMGCR or NPC1L1 inhibition and sarcopenia risk (including ALM and LHGS) in either set of genetic instruments, and sensitivity MR analyses showed consistent estimates, with no statistical evidence of bias from horizontal pleiotropy." (PMID 39254080, 2024). "In this study, we aim to evaluate the causal impacts of the most commonly prescribed lipid-lowering drugs comprised of HMGCR, PCSK9, and NPC1L1 inhibitors on multiple sarcopenia-related traits via the MR approach and provide innovative recommendations for the clinical administration." (PMID 38961447, 2024). "Genetically proxied inhibition of NPC1L1 demonstrated no causal association with all the three sarcopenia-related traits." (PMID 38961447, 2024). "In contrast, inhibition of PCSK9 may reduce appendicular lean mass (beta = -0.050, P = 1.40 × 10− 3), while inhibition of NPC1L1 showed no causal impact on sarcopenia-related traits." (PMID 38961447, 2024). "For the NPC1L1 inhibition, additional analysis using an LD threshold of r2 < 0.3 to increase the number of SNPs as instruments revealed a potential causal association with a lower risk of CHD, and no causal association with any of the three sarcopenia-related traits." (PMID 38961447, 2024).
acne vulgaris (1 paper, 2024). "However, the other three LDL-lowering therapies, targeting HMGCR, NPC1L1, and APOB, showed no significant causal effect on acne vulgaris risk." (PMID 38903813, 2024).
ankylosing spondylitis (1 paper, 2021). An autoimmune chronic inflammatory disorder characterized by inflammation in the vertebral joints of the spine and sacroiliac joints. "The lack of a significant association with PCSK9 score, NPC1L1 score and LDL polygenetic score may imply that simply lowering serum cholesterol levels would be unlikely to contribute to the prevention of ankylosing spondylitis." (PMID 34692687, 2021).
asthma (1 paper, 2015). "Of these, five missense mutations (one each in FAM134B, NPC1L1, IKZF1, SLC26A3 and GSDMB) showed evidence of association with asthma in the combined sample, two of which (IKZF1 and SLC26A3) were more significant in the African ancestry sample." (PMID 25591454, 2015).
breast tumors (1 paper, 2022). "As the target of ezetimibe, inhibition of NPC1L1 can decrease the level of bile-derived cholesterol to inhibit the angiogenesis of breast tumors." (PMID 35151363, 2022).
cholangiocarcinoma (1 paper, 2015). A carcinoma that arises from the intrahepatic biliary tree (intrahepatic cholangiocarcinoma) or from the junction, or adjacent to the junction, of the right and left hepatic ducts (hilar cholangiocarcinoma). "Both cell lines expressed NPC1L1 at similar levels to Huh-7 cells, as measured by Western blotting (data not shown), suggesting that neither of these reported host-cell factors explained the differential permissivity of the cholangiocarcinoma cells to support HCVcc infection." (PMID 25701818, 2015).
choledocholithiasis (1 paper, 2025). Presence or formation of gallstones in the common bile duct. "Therefore, when the expression of NPC1L1 in the liver is reduced, it may lead to the supersaturation of cholesterol in the secreted bile, which makes the formation of choledocholithiasis more likely." (PMID 40463747, 2025).
cholesterol metabolism disorder (1 paper, 2022). "Moreover, it could improve intestinal cholesterol metabolism disorder induced by high-fat and high-cholesterol diets via the reduction of the expression of HMGCR, NPC1L1, ACAT2, MTP, ASBT and IBABP mRNA or protein, increasing ABCG8 mRNA expression." (PMID 36816874, 2022).
colon adenocarcinoma (1 paper, 2023). "Next, NPC1L1 (ENSG00000015520) expression data in colon adenocarcinoma (COAD) and colon adenocarcinoma/rectum adenocarcinoma/esophageal carcinoma (COADREAD) were extracted and transformed by Log2 (transcripts per million + 0.001)." (PMID 36641489, 2023).
colorectal tumors (1 paper, 2015). "At different time points, NPC1L1−/− mice consistently had much fewer colorectal tumors than WT mice." (PMID 25881076, 2015). "Western blot showed that NPC1L1 protein level was high in small intestines while it was undetectable in colorectal mucous membranes or colorectal tumors." (PMID 25881076, 2015). "Western blot was employed to assay NPC1L1 protein in intestine and colorectal tumors." (PMID 25881076, 2015).
Crohn disease (1 paper, 2024). A gastrointestinal disorder characterized by chronic inflammation involving all layers of the intestinal wall, noncaseating granulomas affecting the intestinal wall and regional lymph nodes, and transmural fibrosis. "The SMR analysis showed no significant genetic association between increased gene expression of HMGCR, PCSK9, and NPC1L1 and IBD, Crohn’s disease (CD) and ulcerative colitis (UC)." (PMID 38191425, 2024).
cutaneous melanoma (1 paper, 2024). A primary melanoma arising from atypical melanocytes in the skin. "As for the NPC1L1 and its association with cutaneous melanoma, research is limited." (PMID 38760735, 2024).
cystic kidney disease (1 paper, 2025). A congenital or acquired kidney disorder characterized by the presence of renal cysts. "However, none of the genetic proxies for lipid-lowering drugs (PCSK9 and NPC1L1) targets were found to be causally associated with the risk of cystic kidney disease." (PMID 40289090, 2025). "Therefore, the aim of this study was to evaluate three lipid-lowering drug targets—HMGCR, PCSK9, and NPC1L1—was associated with a decreased risk of cystic kidney disease and PKD." (PMID 40289090, 2025). "Heterogeneity and pleiotropy test in the examined associations and weak instrument statistics between lipid phenotypes mediated by lipid-lowering drug targets (HMGCR, PCSK9, and NPC1L1) and cystic kidney disease and polycystic kidney disease." (PMID 40289090, 2025). "Forest plots showed the MR effect sizes of HMGCR-, PCSK9-, and NPC1L1-mediated LDL-C levels on cystic kidney disease and PKD." (PMID 40289090, 2025). "Indeed, the role of lipid-lowering agents, particularly PCSK9, and Niemann-Pick C1-like 1 (NPC1L1) inhibitors, in cystic kidney disease remains understudied." (PMID 40289090, 2025).
diabetic nephropathy (1 paper, 2025). "Our investigation only revealed the causal relationship between NPC1L1 and diabetic retinopathy but had no statistical significance for diabetic nephropathy and diabetic neuropathy." (PMID 40225015, 2025). "Through MR analysis of these complications, we examined the effects of three common cholesterol-lowering drug targets (HMGCR, PCSK9, and NPC1L1) on three major diabetic microvascular complications: diabetic retinopathy, diabetic nephropathy, and diabetic neuropathy." (PMID 40225015, 2025).
diabetic retinopathy (1 paper, 2025). "Furthermore, NPC1L1 inhibitors can reduce the risk of diabetic retinopathy." (PMID 40225015, 2025). "It is worth noting that our study found the protective effect of NPC1L1 inhibitors on diabetic retinopathy." (PMID 40225015, 2025). "However, NPC1L1 inhibitors may provide protection against diabetic retinopathy." (PMID 40225015, 2025).
epilepsy (1 paper, 2024). A brain disorder characterized by episodes of abnormally increased neuronal discharge resulting in transient episodes of sensory or motor neurological dysfunction, or psychic dysfunction. "Through drug target Mendelian randomization, we systematically assessed the impact of lipid-lowering medications, including HMG-CoA reductase (HMGCR) inhibitors, proprotein convertase subtilisin/kexin type 9 (PCSK9) inhibitors, and Niemann-Pick C1-like 1 (NPC1L1) inhibitors, on epilepsy." (PMID 38523609, 2024).
esophageal adenocarcinoma (1 paper, 2025). A malignant tumor with glandular differentiation arising predominantly from Barrett mucosa in the lower third of the esophagus. "NPC1L1‐mediated LDL was negatively associated with esophageal adenocarcinoma (OR = 0.33, 95% CI: 0.15–0.73, p < 0.01)." (PMID 40443776, 2025).
glaucoma (1 paper, 2024). Increased pressure in the eyeball due to obstruction of the outflow of aqueous humor. "The weighted median (odds ratio [OR] = 0.511; 95% confidence interval [CI], 0.275–0.951; P = 0.034) and IVW-MR analysis (OR = 0.536; 95% CI, 0.308–0.934; P = 0.028) showed that NPC1L1 inhibitors had a significant potential to reduce the risk of glaucoma." (PMID 39140962, 2024). "In summary, our drug-targeted MR analysis study suggested that NPC1L1 inhibitors were associated with a decreased risk of glaucoma." (PMID 39140962, 2024).
gout (1 paper, 2024). A condition characterized by painful swelling of the joints, which is caused by deposition of urate crystals. "Weighted median analysis indicated that NPC1L1 inhibitors could potentially act as a risk factor for gout (OR [95%CI] = 0.53 [-0.02, 1.09], p = 0.0263)." (PMID 39926389, 2024). "In the current investigation, we employed a two-sample Mendelian Randomization analysis approach to explore the relationship between lipid-lowering agents (HMGCR inhibitors, PCSK9 inhibitors, and NPC1L1 inhibitors) and outcomes related to urate and gout." (PMID 39926389, 2024). "In this investigation, the correlation between gene expression of HMGCR, PCSK9, and NPC1L1 and outcomes related to gout and urate was evaluated utilizing the SMR approach." (PMID 39926389, 2024). "Utilizing genetic instruments, our goal was to surmount the constraints inherent in observational studies and to furnish more robust evidence for the potential role of HMGCR, PCSK9, and NPC1L1 in the onset of gout and urate." (PMID 39926389, 2024). "Specifically, the limited sample size of NPC1L1 eQTL within the GTEx program, coupled with the absence of NPC1L1 eQTL data in blood samples, might have resulted in an underestimation of the efficacy of NPC1L1 inhibitors in managing gout and urate." (PMID 39926389, 2024).
Hypocholesterolemia (1 paper, 2021). An decreased concentration of cholesterol in the blood. "Ezetimibe, the potent cholesterol absorption inhibitor that targets NPC1L1, is one of the effective medications for hypocholesterolemia." (PMID 34829135, 2021).
hypothyroidism (1 paper, 2025). Abnormally low levels of thyroid hormone. "The effect of treatment (hypothyroidism) was significant for Slc27a4, Npc1l1, Slc2a2 and Slc2a5." (PMID 39958687, 2025). "In parallel, NPC1L1 content in female enterocytes was not altered by hypothyroidism." (PMID 39958687, 2025).
iliac artery aneurysms (1 paper, 2021).
Infertility (1 paper, 2023). "Through a large-scale MR analysis of female reproductive endocrine diseases using data from a Finnish database, we investigated the effects of three common drug targets (HMGCR, PCSK9, and NPC1L1) on various conditions including PCOS, POF, PMS, menorrhagia, oligomenorrhea, and infertility." (PMID 38027179, 2023).